CD34 (CD34 molecule)
Diseases named in the same sentence as CD34 in open-access papers (continued):
Sharing a sentence is not in itself a finding about the gene and the disease.
dermatofibroma (20 papers, 2010 to 2026). "Strong CD34 positivity remains a hallmark diagnostic feature and serves to differentiate DFSP from benign entities such as dermatofibroma." (PMID 41151362, 2025). "Immunohistochemically, DFSP is CD34 positive and immunohistochemical staining for CD34 is often used for differential diagnosis from dermatofibroma." (PMID 31138233, 2019). "at the Tohoku University first discovered that the expression of the CD34 could be used as a new method to distinguish DFSP from other fibrohistiocytic tumors." (PMID 39600645, 2024). "CD34 immunoreactivity has been shown to be useful in distinguishing DFSP from fibrohistiocytoma (dermatofibroma), especially when dealing with small biopsies, although cutaneous fibrohistiocytomas may sometimes show focal and weak expression of this immunomarker." (PMID 33445443, 2021). "CD34 is a useful marker that allows differentiation of DFSP tumor cells from normal stroma cells and dermatofibroma (DF)." (PMID 20525288, 2010). "CD34 and S100 immunohistochemistry were both negative, ruling out the differential diagnoses that included dermatofibroma." (PMID 39104649, 2024). "Immunohistochemistry for CD34 and S100 were both negative, ruling out a differential diagnosis of dermatofibroma." (PMID 39104649, 2024). "In tumor cells of the lesion, the factor XIIIa positivity confirms dermal dendrocyte differentiation, the neoplastic component central to dermatofibroma formation, while CD34 negativity excludes vascular proliferation and aids in distinguishing MEDFs from DFSP." (PMID 41280943, 2025). "DFSP stains positive for CD34 and vimentin and negative for S100, factor XIIIa, podoplanin D2-40, stromelysin III, and cathepsin K. This helps differentiate DFSP from benign entities such as dermatofibroma." (PMID 41393578, 2025). "In particular, the most common misleading diagnosis was that of dermatofibroma—the benign counterpart of DFSP—generally composed of a mixture of spindle cells and inflammatory cells, with a minor subcutaneous involvement, that could be differentiated from DFSP by negative staining for CD34." (PMID 38201649, 2024).
ischemic stroke (20 papers, 2011 to 2024). A stroke disorder caused by obstruction of blood flow to the brain, due to thrombotic (local blood clot formation) or embolic (due to a blood clot or other material traveling from another site) event. "Another study reported that a reduction in the number of endothelial progenitor cells (CD34-positive cells) is associated with an increase in the number of infarctions in patients with ischemic stroke." (PMID 26769093, 2016). "The action of endogenous mobilised CD34+ cells have been studied in response to a neurological insult, most commonly ischemic stroke and TBI." (PMID 39075614, 2024). "Further, higher levels of circulating CD34+ cells have been detected in humans who have experienced an ischemic stroke." (PMID 39075614, 2024). "Preclinical studies have highlighted the benefits of unexpanded CD34+ cells in neurological conditions, specifically for ischemic stroke, as well as the differentiation and homing ability in response to brain injury." (PMID 39075614, 2024). "G‐CSF has also shown the potential to effectively mobilize bone marrow CD34+ stem cells in patients with recent ischemic stroke." (PMID 37786546, 2023). "It has been reported that CD34+ cells induce therapeutic angiogenesis in several ischemic diseases, including myocardial ischemia, ischemic stroke, and ischemic hindlimb." (PMID 37566085, 2023). "CD34+ stem cells also effectively mobilized and appeared to be safe and well tolerated after G-CSF injection when treatment is delayed for month in ischemic stroke patients." (PMID 22007348, 2011). "Mobilisation of CD34+ cells has also been detected in the setting of ischemic stroke." (PMID 39075614, 2024). "There were different levels of CD34+KDR+ EPC-EXs at different times during ischemic stroke, which may be used as biomarkers for diseases and indicators for the prognosis of and therapeutic efficacy for ischemic stroke." (PMID 34513956, 2021). "Therefore, the aim of this study was to evaluate whether the protective effect of Angpt2 against ischemic stroke correlates with enhanced angiogenesis by utilizing the length and area of CD34+ blood vessels as the deciding references for angiogenic activities after cerebral ischemia." (PMID 36358355, 2022). "The Pseudo-time series analysis found that the expression of MRPS12 decreased gradually with the differentiation of pre-B cell CD34 cells in ischemic stroke, suggesting that the downregulation of MRPS12 expression may play an important role in ischemic stroke." (PMID 37418282, 2023). "However, recent observation of a close correlation between baseline CD34+KDR+ and CD133+KDR+ counts and the outcome of stroke supports the idea that these particular EPC subtypes can be used as potential prognostic markers for ischaemic stroke." (PMID 38247804, 2024).
Kaposi's sarcoma (20 papers, 2008 to 2025). A malignant neoplasm characterized by a vascular proliferation which usually contains blunt endothelial cells. "In contrast, Kaposi sarcoma shows CD34 expression on both endothelial cells and perivascular spindle cells." (PMID 41523513, 2025). "Subsequent PET/CT detected metabolically active nodes on the contralateral side, and additional biopsies confirmed Kaposi sarcoma, with immunohistochemistry positive for CD34 and ERG." (PMID 41246668, 2025). "The immune infiltrate was also investigated in a rare case of Kaposi sarcoma developed in a renal allograft ureter, where CD34, together with HHV8, defined the diagnosis." (PMID 35890003, 2022). "Though the CD31 & CD34 immuno-stains recognize the lesion as endothelial origin, the HHV8 antigen immuno- reactivity in the tissue is diagnostic for Kaposi sarcoma." (PMID 31827596, 2019). "The cellularity and extravasation of red blood cells simulated a Kaposi sarcoma, necessitating a test for CD34, which is positive in Kaposi sarcoma." (PMID 31610454, 2019). "Intravascular Kaposi's sarcoma is a newly recognized morphologic variant characterized by an exclusive intravascular growth of interlacing fascicles of human herpesvirus-8, CD31- and CD34-positive spindle cells." (PMID 18513426, 2008). "Histopathology showed a fusiform spindle cell proliferation with slit-like vascular spaces, showing immunohistochemical positivity for CD34 and HHV-8, consistent with Kaposi sarcoma." (PMID 41555982, 2025). "Histopathology showed a spindle cell proliferation arranged in intersecting fascicles with slit-like vascular spaces and extravasated erythrocytes, with immunohistochemical expression of CD34 and HHV-8, confirming Kaposi sarcoma." (PMID 41555982, 2025). "Nevertheless, Kaposi sarcoma stains are positive for CD31, CD34 and D2-40, and patients are also positive for HHV-8." (PMID 36832159, 2023). "Kaposi’s sarcoma has a prominent lymphoplasmacytic infiltrate and is immunoreactive for CD31, CD34, and HHV8." (PMID 35615157, 2022). "The pathological report revealed Kaposi sarcoma, characterized by spindle-shaped tumor cells arranged in vascular spaces, positive for CD34, SMA, and HHV-8, negative for desmin." (PMID 39460334, 2024). "Using a reverse flow cytometric gating strategy with Lin- selection stain (which includes anti-CD3, -CD19, -CD20, -CD14, -CD16, -CD56 mAbs) Lin-CD34+DNAM-1bright precursor cells could be detected in all the patients with non-Hodgkin Lymphoma, NSCLC and Kaposi Sarcoma." (PMID 38390333, 2024). "Immunohistochemically, AH exhibits CD31, CD34, and ERG positivity, but it is negative for HHV-8, CD8, and D2-40, which helps exclude Kaposi sarcoma and lymphatic-derived lesions." (PMID 40364141, 2025). "The tumor was positive for cluster of differentiation 31 (CD31), CD34, and HHV-8 immunostains and negative for smooth muscle antibody (SMA) and desmin immunostains, consistent with Kaposi sarcoma." (PMID 33754107, 2021). "Kaposi's sarcoma is immunoreactive with endothelial cell markers such as CD31 and CD34, and negative for muscle specific antibodies." (PMID 21437186, 2011).
liposarcoma (20 papers, 2008 to 2025). A usually painless malignant tumor that arises from adipose tissue. "CD34 immunohistochemical staining was used to measure microvessel density (MVD) in 89 retroperitoneal liposarcoma tissues." (PMID 34868934, 2021). "CD34 Immunohistochemistry aids in determining SCL from liposarcoma." (PMID 39013244, 2024). "In addition to liposarcoma, CD34-positive cells with stem cell gene expression and functional characteristics have also been reported in normal fat and benign lipomas." (PMID 27376027, 2016). "Pleomorphic liposarcoma may contain large numbers of pleomorphic giant cells; however, the characteristic finding is the presence of multivacuolated pleomorphic lipoblasts, possibly showing CD34 and S100 positivity." (PMID 40725486, 2025). "S100, CD34, and others may be helpful (as well as cytogenetic techniques) as they can identify aberrations indicating myxoid/round cell sarcoma; however, they cannot identify liposarcoma cells with absolute certainty." (PMID 18959781, 2008). "Liposarcomas express specifically HMGA2, MDM2 and myxoid liposarcomas express specifically CD34 and DDIT13." (PMID 39862670, 2025). "On the other hand, well-differentiated liposarcomas consist of atypical, hyperchromatic stromal cells and are negative for CD34 and positive for MDM2 and CDK4." (PMID 40777097, 2024). "Immunohistochemical analysis of SCL typically shows spindle cells that are positive for CD34 and negative for S-100, which helps differentiate SCL from other lipomatous tumors, such as well-differentiated liposarcoma (WDL)." (PMID 39925511, 2025). "The CD34 immunohistochemistry examination is essential to confirm the diagnosis, showing positive results in SCL and negative results in liposarcoma." (PMID 39013244, 2024). "Immunohistochemistry tests, such as CD34, can also help distinguish SCL from liposarcoma, although they are not specific." (PMID 39013244, 2024). "Case 4 with negative staining for CD34 and absence of a detectable gene fusion showed strong nuclear expression of STAT6 and no MDM2 amplification, so the possibility of being a dedifferentiated liposarcoma was ruled out." (PMID 25432794, 2014).
myeloid neoplasm (20 papers, 2009 to 2025). Proliferation of myeloid cells originating from a primitive stem cell. "For example, in a non-MRD iteration of a precursor antibody panel, CD13 and HLA-DR expression patterns have been extensively evaluated in our laboratory on CD34-positive myeloblasts, in normal controls, and in individuals with myeloid neoplasms." (PMID 40227672, 2025). "To assess the changes in RP expression levels in human myeloid neoplasms, we performed gene expression analysis of CD34+ hematopoietic progenitor cells of 183 patients with MDS." (PMID 41389200, 2025). "Another well-described characteristic of EVs in myeloid neoplasms is their ability to suppress healthy hematopoiesis either via direct effect on healthy CD34+ cells or via alteration of the differentiation of BMM cells." (PMID 35955960, 2022). "p200 was also the predominant isoform in primary human CD34+ hematopoietic stem and progenitor cells (HSPCs), the normal counterpart thought to give rise to myeloid malignancies." (PMID 34997000, 2022). "On the contrary, CD9 appears to be a significant element in leukemic cell development, and its expression is upregulated in CD34+ cells from patients affected by myeloid neoplasms and in multiple myeloma cells." (PMID 33918035, 2021). "Like in other myeloid neoplasms, these cells are considered to reside in a CD34+ fraction of the clone." (PMID 32326377, 2020). "According to these results, WPB, WBM and CD34-positive cells were used as controls for myeloid neoplasms and CD3-positive T-cells as controls for T-cell neoplasms." (PMID 19750229, 2009). "Given their important role in CMML pathogenesis, such epigenetic alterations could account for the decreased expression of CXCL8 receptors on CMML CD34+ cells, in contrast with other myeloid malignancies." (PMID 39545419, 2024). "Thus, in vitro studies using CD34+ HSPC from FHs as healthy controls in experimental set-ups examining myeloid malignancies should be interpreted with caution." (PMID 36882822, 2023). "Besides this, alterations in this gene have been also reported in CD34+ cells of patients with myeloid malignancies." (PMID 28399885, 2017). "To further examine the distribution of 5hmC with other epigenetic marks in patients with myeloid neoplasms, we analyzed the 5hmC enrichment profile within the published DNase I hypersensitive site and histone modification (H3K4me1 and H3K27ac) regions collected from human CD34 + cells." (PMID 35765052, 2022). "Around 60% of CD34+ cells from patient 2 [P2(h)] exhibited a heterozygous JAK2V617F mutation (JAK2V617F/WT) whereas no mutation was identified in these cells in ASXL1 and the other genes involved in myeloid malignancies, including TET2, EZH2, DNMT3A, IDH1 and SRSF2." (PMID 24066127, 2013). "The following surface antigens were selected for analysis: for myeloid tumors: MV-4-11, Thp-1, HL-60—CD11b, CD14, K562 and KG-1—CD34, and CD38; for lymphoid neoplasms: Raji, Daudi, U2932—CD19, CD20, Jurkat—CD4, CD8." (PMID 35053549, 2022). "Finally, the CD9 upregulation in HSCs observed previously in patients affected by myeloid neoplasms could be a reflection of an increase in total CD34+ stem cells, including VSELs, since our study is the first to differentiate the expression of CD9 between the two types of stem cells." (PMID 33918035, 2021). "As in other myeloid neoplasms, MPN-SC are considered to reside within the CD34+/CD38− population of the clone." (PMID 32326377, 2020). "Recently, it has been demonstrated that it is a specific marker expressed on LSCs of CML, both in BM and PB samples, and absent on CD34+/CD38− stem cells in normal subjects or on LSCs of other myeloid neoplasms." (PMID 35205639, 2022). "We screened 1,346 patients having undergone HCT for myeloid neoplasms at our center from 1996 to 2016; 443 patients with data on total peripheral blood mononuclear cells (PBMC)/CD4+/CD34+ short tandem repeat (STR) donor chimerism (DC) and follow-up ≥24 months post-HCT were included." (PMID 34950586, 2021).
myeloid neoplasm (continued). "On the other hand, most megakaryocytes in the normal/reactive BM usually are CD34-negative, so that a clear-cut expression of CD34 in a majority of megakaryocytes must be regarded as phenotypic aberrancy supporting the conclusion the patient suffers from a myeloid neoplasm such as MDS." (PMID 21317447, 2010).
Obesity (20 papers, 2012 to 2026). Accumulation of substantial excess body fat. "Body mass index has a significant role to play in progenitor cell population and their mobilization with majority of the reports indicating that higher BMI and obesity are associated with increased CD34+ cell counts." (PMID 22830032, 2012). "It is plausible that CD34+ cells play key role in obesity-associated inflammation since obesity is associated with elevated levels of inflammation and that CD34+ cells contribute to the elevated inflammation by secreting MCP-1." (PMID 23216800, 2012). "In particular, a study showed increases in cord blood CD34+CD38− stem cell and CD34+ progenitor cell concentrations with maternal obesity, suggesting that the higher proportions of stem cells in cord blood may make the babies more susceptible to obesity and cancer risks." (PMID 40388307, 2025). "BMI has a significant role in determining the CD34+ cell count and mobilization, and the majority of reports indicate that the greater the BMI and obesity are, the more critical the CD34+ cell count." (PMID 38774070, 2024). "Previous studies reported low circulating HSC numbers in elderly individuals and that obesity promotes the mobilization of CD34+ progenitor cells." (PMID 36686976, 2023). "New studies using transmission electron microscopy are required and on the behaviour of TCs/CD34+SCs in other pathologic processes of the adipose tissue, specifically in lipomatosis and obesity." (PMID 33353193, 2020). "Given the number of cytokines associated with fibrocyte recruitment and differentiation that are upregulated in obesity, fibrocytes from CD11b+CD34+ cells could be longer lived in obese mice, leading to increased SMA+ CAFs in tumors of obese mice." (PMID 38041006, 2023). "Further studies are required on adipose tissue TCs/CD34+SCs, mainly in lipomatosis and obesity." (PMID 33353193, 2020). "To assess the effects of overweight/obesity on angiogenesis in tumor-adjacent adipose tissue, we used CD31 and CD34 as endothelial markers for microvessel formation." (PMID 39456610, 2024). "Therefore, a key link in the negative association between CD34+ cell count and obesity could be TNFα, one of the most important inhibitors of haematopoiesis in the bone marrow, both in the basal state and after G-CSF stimulation." (PMID 37895025, 2023). "The MSCA1+ cell subset is markedly increased with obesity in SCAT, and the adipogenic potential of whole CD34+ progenitor cells is markedly higher in SCAT than VSAT from obese women." (PMID 31186409, 2019). "The observed expression of CD34, a marker not expressed by bone marrow MSCs41, suggests that MSCs circulating in obesity are ASCs mobilized from WAT." (PMID 27241286, 2016). "Consistent with previous studies in diet-induced obesity in mice, our cohorts of HFD mice exhibited leukocytosis and monocytosis (CD115+Ly6G−Ly6C+) in the blood and increased abundance of myeloid compartments such as GMP cells (Lin−Sca1−cKit+FcγR+CD34+) in the BM but showed unaltered LSK HSPCs." (PMID 40795290, 2025). "By immunohistochemical analysis, we found that a high percentage of cells within tumor-neighboring and -infiltrating adipose tissue of patients with obesity are CD34 + /CD45-, while lacking the expression of CD31, indicating their ASC identity in both primary and metastatic CRC." (PMID 34408135, 2021).